DOCK3 (dedicator of cytokinesis 3)
Description:
Potential guanine nucleotide exchange factor (GEF). GEF proteins activate some small GTPases by exchanging bound GDP for free GTP. Its interaction with presenilin proteins as well as its ability to stimulate Tau/MAPT phosphorylation suggest that it may be involved in Alzheimer disease. Ectopic expression in nerve cells decreases the secretion of amyloid-beta APBA1 protein and lowers the rate of cell-substratum adhesion, suggesting that it may affect the function of some small GTPase involved in the regulation of actin cytoskeleton or cell adhesion receptors (By similarity).
Synonyms: PBP; KIAA0299; MOCA; NEDIDHA
Tractability: Antibody: its Gene Ontology location is reachable by antibodies, with medium confidence. PROTAC: its protein half-life has been measured.
Gene: Protein-coding gene on chromosome 3 (50,674,927 to 51,384,198, forward strand). Ensembl gene ENSG00000088538.
Subcellular location: Cytoplasm
Subcellular location (Human Protein Atlas): Cytosol
Pathways (Reactome):
Signal Transduction: NTRK2 activates RAC1; RAC1 GTPase cycle; RAC2 GTPase cycle; RHOG GTPase cycle
Hemostasis: Factors involved in megakaryocyte development and platelet production
Gene Ontology:
Molecular function: protein binding; guanyl-nucleotide exchange factor activity; small GTPase binding; GTPase activator activity
Biological process: neurotrophin TRK receptor signaling pathway; regulation of small GTPase mediated signal transduction; small GTPase-mediated signal transduction
Cellular component: cytosol; cytoplasm; plasma membrane
Genetic constraint (gnomAD): Loss-of-function variants: 56 observed, 234.61 expected, observed/expected ratio (o/e) 0.24, 90% interval 0.19 to 0.3. The upper end of that interval is the gene's LOEUF score, 0.3, which puts it in group 1 of 6, group 1 being the genes least tolerant of losing a copy. Missense variants: 1,860 observed, 2,456.8 expected, observed/expected ratio (o/e) 0.76, 90% interval 0.73 to 0.79. Synonymous variants: 828 observed, 891.95 expected, observed/expected ratio (o/e) 0.93, 90% interval 0.88 to 0.98.
Homologues: Orthologues: chimpanzee DOCK3 (99% identical), rabbit DOCK3 (99% identical), dog DOCK3 (99% identical), pig DOCK3 (99% identical), rat Dock3 (98% identical), mouse Dock3 (98% identical), macaque DOCK3 (97% identical), guinea pig DOCK3 (96% identical), zebrafish dock3 (80% identical), tropical clawed frog dock3 (78% identical), Caenorhabditis elegans ced-5 (23% identical), Drosophila melanogaster Zir (13% identical), and 1 more. Paralogues in human: DOCK4 (56% identical), DOCK1 (35% identical), DOCK5 (34% identical), DOCK2 (34% identical), DOCK11 (16% identical), DOCK9 (16% identical), DOCK10 (15% identical), DOCK6 (15% identical), DOCK7 (15% identical), DOCK8 (15% identical).
Diseases named in the same sentence as DOCK3 in open-access papers:
DOCK3 is named in the same sentence as 86 diseases in open-access papers, as found by Europe PMC text mining. Sharing a sentence is not in itself a finding about the gene and the disease. The quoted sentences say what the papers report.
Alzheimer disease (6 papers, 2011 to 2023). A progressive, neurodegenerative disease characterized by loss of function and death of nerve cells in several areas of the brain leading to loss of cognitive function such as memory and language. "DOCK3 is also associated with Alzheimer’s disease (AD), and its expression is reduced from the soluble fraction of AD brain compared with the age-matched controls." (PMID 37188749, 2023). "Distinct from this role in the pathogenesis of Alzheimer’s disease, Dock3 has recently also been suggested to attenuate NMDA-mediated neurotoxicity and in doing so, prevent excitotoxic cell death." (PMID 25309324, 2014). "Dock3 may be linked to the pathogenesis of Alzheimer’s disease: it is absent from the soluble fraction of samples taken from Alzheimer’s disease brains, accumulates in neurofibrillary tangles, and regulates Aβ secretion." (PMID 23641686, 2013). "Identification of chemical compounds that can increase the expression of Dock3, or otherwise reduce the surface expression of NR2D, might have therapeutic benefit for the treatment of neurodegenerative disorders such as Alzheimer’s disease and glaucoma." (PMID 23641686, 2013).
melanoma (6 papers, 2010 to 2025). A malignant, usually aggressive tumor composed of atypical, neoplastic melanocytes. "Studies have shown that DOCK3 overexpression enhances the aggressiveness of tumors, including melanomas, by promoting amoeboid invasion." (PMID 41200217, 2025). "In contrast, DOCK3 was shown to rather regulate cells amoeboid features and silencing of DOCK3 increased the proportion of melanoma cells that invade a 3D matrices in an amoeboid manner." (PMID 32526908, 2020). "DOCK3 is known as a modifier of cell adhesion (MOCA) and presenilin-binding protein (PBP), which has an important role in melanoma." (PMID 35439935, 2022). "In melanoma cells, mesenchymal migration was driven by activation of RAC via a complex of a Rac guanine nucleotide exchange factor DOCK3 and the adaptor protein NEDD9 (melanoma metastasis gene)." (PMID 28499439, 2017). "Mesenchymal melanoma morphology and invasiveness style is controlled by a Rac1 activation pathway, mediated by adaptor protein NEDD9 and DOCK3, acting as a Rac1-GEF." (PMID 20822528, 2010). "Resolving the issue of how Spg integrates with the other signals that regulate MAPK activity could also be rather useful, given that DOCK3 and DOCK4 were previously shown to be required for the migration of melanoma and breast cancer cells, respectively, via activation of the Rho GTPase Rac." (PMID 30018198, 2018).
Ataxia (5 papers, 2020 to 2025). Ataxia refers to impaired coordination of voluntary muscle movement. "More specifically, biallelic pathogenic variants in DOCK3 leading to a loss of function have been recently involved in the pathogenesis of a neurodevelopmental disorder with impaired intellectual development, hypotonia, and ataxia (NEDIDHA, OMIM # 618292)." (PMID 34943902, 2021). "Other genes are related to cytoskeleton remodeling, including Cdh4, Pcdh9, Dock5, Dock3 for the proprioceptors (mutation of Dock3 is known to results in ataxia) and Stom and Pdlim1 for mechanoreceptors, as well as ion channels (Asic1 and Kcnip2 for proprioceptive fate)." (PMID 32826903, 2020). "In particular, coordination or gait abnormalities, e.g. ataxia, were present in all DOCK3 individuals and in the majority of individuals (individuals 1, 2, 3, 4 and 7) in the present study." (PMID 38526744, 2024).
glaucoma (4 papers, 2013 to 2025). Increased pressure in the eyeball due to obstruction of the outflow of aqueous humor. "Since glaucoma is the second leading cause of blindness in the world, and the number of patients is increasing in the aging society, other low-molecular-weight compounds that have neuroprotective effects may be useful in combination with DOCK3 activator." (PMID 37188749, 2023). "These insights suggest that targeting Src signalling could provide neuroprotection in glaucoma, offering a strategy to counteract fibrosis-related damage, excitotoxicity, and oxidative stress, with Dock3 signalling as a promising therapeutic target." (PMID 39940776, 2025). "Our findings suggest that the low-molecular-weight DOCK3 activators could be a potential therapeutic candidate for treating axonal injury and neurodegenerative diseases including glaucoma." (PMID 37188749, 2023). "Considering the situation, low-molecular-weight DOCK3 activator may be useful to treat retinal degenerative disorders including glaucoma." (PMID 37188749, 2023). "Additionally, Dock3 has been shown to mitigate oxidative damage through suppression of the apoptosis signal-regulating kinase 1 (ASK1) pathway, which is activated in response to cellular stress and is implicated in RGC loss in glaucoma models." (PMID 39940776, 2025). "Furthermore, overexpression of DOCK3 promotes neuroprotection in a mouse model of glaucoma." (PMID 37188749, 2023). "Furthermore, Dock3 has been shown to bind to NMDA receptors, decreasing their expression in a mouse model of glaucoma (glutamate/aspartate transporter knockout)." (PMID 30373222, 2018).
attention deficit-hyperactivity disorder (3 papers, 2009 to 2024). A disorder characterized by a marked pattern of inattention and/or hyperactivity-impulsivity that is inconsistent with developmental level and clearly interferes with functioning in at least two settings (e.g. at home and at school). "Rs17659990 is an intronic variant of dedicator of cytokinesis 3 (DOCK3) gene, a gene specifically expressed in the central nervous system, that was associated with an attention deficit hyperactivity disorder-like phenotype." (PMID 29228715, 2017). "Although DOCK3 is expressed in colon tissues, it is mostly known for its role in cytoskeleton organization and cell-matrix modeling, and as such has been reportedly investigated as a stimulator of axonal growth or in conditions such as attention-deficit hyperactivity disorder." (PMID 39025327, 2024).
autoimmune disease (2 papers, 2017 to 2023). A disorder resulting from loss of function or tissue destruction of an organ or multiple organs, arising from humoral or cellular immune responses of the individual to their own tissue constituents. "The random forest classification predicted ZNF804A, ANK3 and DOCK3 that have so far not been connected to SLE or any other autoimmune disease to be risk genes for SLE." (PMID 28740209, 2017).
breast carcinoma (2 papers, 2017 to 2018). "Among these, 11 CNVRs overlapped with 12 genes (GSTM2, RAB40B, HLA_DRB5, HLA_DRB6, EYA1, DOCK3, ANKS1B, CACNA1C, RAB11FIP3, BAGE, SGCZ, POM121c) and were specifically associated with breast cancer risk and OS." (PMID 29116104, 2017).
colorectal cancer (2 papers, 2017 to 2025). A primary or metastatic malignant neoplasm that affects the colon or rectum. "A genome-wide significant association of rs17659990 (P=5.43×10-9, DOCK3, chromosome 3p21.2) with colorectal cancer risk was observed." (PMID 29228715, 2017). "Previous studies have shown that DOCK3 is associated with the development of colorectal cancer and serves as an independent prognostic risk factor for colorectal adenocarcinoma, making it a promising biomarker for prognosis prediction in colorectal cancer." (PMID 41200217, 2025).
neuroblastoma (2 papers, 2011 to 2013). Neuroblastoma (NB) is the most common solid, extracranial childhood tumor. "To investigate whether Dock3 suppresses the surface expression of NR2D, we used N2A neuroblastoma cells." (PMID 23641686, 2013).
retinal degeneration (2 papers, 2016 to 2018). Degeneration of the retina. "Overexpression of Dock3 also contributes to both neuroprotection and axon regeneration in retinal degeneration induced by optic nerve injury model and demyelinating model." (PMID 26784179, 2016). "Similarly, overexpression of dedicator of cytokinesis 3 (Dock3), an atypical guanine exchange factor, inhibits the ASK1-p38 pathway and decreases retinal degeneration after optic nerve injury." (PMID 30373222, 2018).
Sepsis (2 papers, 2023 to 2025). Sepsis is defined as life-threatening organ dysfunction caused by a dysregulated host response to infection. "Together, these results demonstrate that DOCK3 is essential for the protective role of ZBED6 deficiency on sepsis‐induced muscle atrophy." (PMID 37551034, 2023). "The loss of ZBED6 upregulates the expression of DOCK3, leading to the hyperactivation of its downstream RAC1/PI3K/AKT signalling cascade, which in turn attenuates sepsis‐induced muscle atrophy." (PMID 40464206, 2025). "DOCK3 overexpression was sufficient to rescue aggravated sepsis‐induced atrophy in ZBED6‐overexpressing myotubes." (PMID 37551034, 2023). "In septic ZBED6‐deficient pigs, DOCK3 expression is increased in skeletal muscle and myocytes, activating the RAC1/PI3K/AKT pathway and protecting against sepsis‐induced muscle wasting." (PMID 37551034, 2023). "ZBED6 deficiency increased DOCK3 expression, leading to hyperactivation of its downstream RAC1/PI3K/AKT signaling cascade, thus preventing sepsis‐induced muscle atrophy." (PMID 37551034, 2023). "Additionally, ZBED6‐KO is associated with elevated muscle growth rates and higher muscle mass in pigs and mice and has been shown to protect against sepsis‐induced muscular atrophy in pigs by targeting DOCK3." (PMID 40464206, 2025). "Notably, sepsis patients show increased ZBED6 expression along with reduced DOCK3 and downregulated RAC1/PI3K/AKT pathway." (PMID 37551034, 2023). "Knockdown of DOCK3 in myotubes abolished the resistance to sepsis‐induced myotube atrophy by ZBED6 shRNAs, showing reduced myotube diameter and elevated ARTOGIN‐1, suggesting that ZBED6 knockdown protects myotubes from sepsis‐induced atrophy by upregulating DOCK3." (PMID 37551034, 2023). "Our study extended a protective role of DOCK3 in sepsis‐induced muscle atrophy and elucidated its upstream transcription factor ZBED6 and downstream RAC1/PI3K/AKT pathway, revealing a novel regulatory mechanism of DOCK3 underlying the occurrence of muscle atrophy." (PMID 37551034, 2023). "In contrast, skeletal muscles from sepsis patients with muscle atrophy showed significantly increased protein levels of ZBED6 and reduced levels of DOCK3/RAC1‐GTP/p‐AKT." (PMID 37551034, 2023). "In contrast, ZBED6 overexpression in myotubes exacerbated sepsis‐induced muscle atrophy, exhibiting small myotube diameter and high expression levels of ATROGIN‐1, accompanied with reduced levels of DOCK3." (PMID 37551034, 2023).
asthma (1 paper, 2022). "Although a previous study suggested that DOCK3 could have a role in lung cancer, to date we are not aware of its implication in asthma." (PMID 36395113, 2022).
colon adenocarcinoma (1 paper, 2018). "For example, loss of function mutations in RNF43 and DOCK-3 genes were associated with higher infiltration of CD8+ T cells in colon adenocarcinoma (COAD)." (PMID 30622534, 2018).
colorectal adenocarcinoma (1 paper, 2018). The most common type of colorectal carcinoma. "For example, a novel association was detected between mutations in two different modulators of the Wnt signaling pathway (RNF-43 and DOCK3) and increased CD8+ T cell infiltration in colorectal adenocarcinoma (COAD)." (PMID 30622534, 2018).
colorectal tumors (1 paper, 2024). "Nonetheless, we observed some nominally significant differential associations in 12 genes, including positive associations between folate intake and the risk of CHD1-, DOCK3-, and ZNF521-mutated colorectal tumors, which warrant replication in future studies." (PMID 39025327, 2024).
Creutzfeldt-Jakob disease (1 paper, 2022). "Similarly, the dedicator of cytokinesis, DOCK3 (also known as modifier of cell adhesion - MOCA and presenilin-binding protein - PBP), is another important protein involved AD progression and several other neurological deficiencies, including tauopathies and Creutzfeldt-Jakob disease." (PMID 35292653, 2022).
Duchenne muscular dystrophy (1 paper, 2023). Duchenne muscular dystrophy (DMD) is a neuromuscular disease characterized by rapidly progressive muscle weakness and wasting due to degeneration of skeletal, smooth and cardiac muscle. "In Duchenne muscular dystrophy (DMD), a progressive X-linked neuromuscular disorder, DOCK3 expression is increased; however, the increased expression is observed along with a subsequent decrease in the levels of activated RAC1 due to skeletal myofiber membrane instability." (PMID 37895289, 2023).
Hyperglycemia (1 paper, 2024). An increased concentration of glucose in the blood. "Conditional knockout mice lacking DOCK3 in skeletal muscle (Dock3 mKO) exhibit pronounced hyperglycemia and increased fat accumulation, suggesting a role for DOCK3 in metabolic regulation." (PMID 39616183, 2024).
Intellectual disability (1 paper, 2023). "Biallelic variants in DOCK3 associated with complete or partial loss of function of the gene were recently reported in six patients with intellectual disability and muscle hypotonia." (PMID 37895289, 2023). "Questions remain as to how to best treat DOCK3 loss-of-function patients as these patients suffer from intellectual disability and muscle hypotonia from an early age, with them often having difficulty obtaining an official genetic diagnosis without genomic testing." (PMID 37895289, 2023).
non-small cell lung carcinoma (1 paper, 2020). A group of at least three distinct histological types of lung cancer, including non-small cell squamous cell carcinoma, adenocarcinoma, and large cell carcinoma. "DOCK3 (a RAC1-GEF) has been shown to regulate cell adhesion in non-small cell lung cancer cells." (PMID 33057364, 2020).
prostate carcinoma (1 paper, 2025). A carcinoma that arises from epithelial cells of the prostate gland. "By integrating bulk RNA-sequencing (TCGA-PRAD), single-cell RNA-sequencing (GEO), and genomic data, we explored the expression characteristics of DOCK3 in prostate cancer and its potential as a therapeutic target." (PMID 41200217, 2025). "In conclusion, our comprehensive multi-omics analysis reveals DOCK3 as a critical nexus connecting genomic instability, metastatic behavior, and immune microenvironment remodeling in prostate cancer." (PMID 41200217, 2025). "Our study identified DOCK3 as a crucial player in PCa, particularly highlighting its ​novel dual role in promoting metastasis while concurrently modulating immune infiltration—a phenomenon not extensively reported in prostate cancer prior to this work." (PMID 41200217, 2025).
prostate tumor (1 paper, 2025). "DOCK3 expression was significantly elevated in prostate tumor compared to normal tissues (p < 0.05), supporting its potential role as a biomarker." (PMID 41200217, 2025).